LEP (leptin)
Diseases named in the same sentence as LEP in open-access papers (continued):
Sharing a sentence is not in itself a finding about the gene and the disease.
Insulin resistance (continued). "As the ß-estimates in our study and the results from the random forest analysis also point towards a stronger association of leptin to the metabolome compared to insulin to the metabolome, this finding of ours might be explained by early stages of insulin resistance or fatty liver in some children." (PMID 28817652, 2017). "In addition to contributing to enhanced CV risk through metabolic pathways related to adiposity and insulin resistance, adiponectin and/or leptin could therefore have independent effects as well." (PMID 28068986, 2017). "Since leptin seems to be more of a protective hormone, we can speculate that may be oxidative stress induced hyperleptinemia causes an aberrant leptin signaling (leptin resistance), thus rendering leptin from its protective effects and inducing insulin resistance in obese people." (PMID 25897417, 2015). "The result of our meta-analysis suggested that metformin administration was significantly associated with the reduction in circulation leptin concentration and that delaying or preventing the occurrence of insulin resistance and diabetes might be beneficial in patients with PCOS." (PMID 26473366, 2015). "Modulation of adipocytokines production (i.e., increased serum adiponectin and decreased serum leptin) may also underlie the improvement of insulin resistance and could be a possible mechanism for the beneficial cardiovascular effects of metformin and sitagliptin." (PMID 25838947, 2015). "It is hard to say without any in vivo model that whether it is hyperleptinemia which induces oxidative stress in obese subjects and makes them susceptible to insulin resistance or is it oxidative stress which is causing an abrupt increase in leptin, thus mediating its harmful effects." (PMID 25897417, 2015). "The underlying mechanism is open to speculation but may include persistence of the central leptin and insulin resistance associated with DIO and/or dominance of gut satiety hormone (PYY) signalling over the metabolic hormone feedback to hypothalamic appetite regulatory pathways." (PMID 26447990, 2015). "Furthermore, these authors noted that the impairment of autonomic cardiaccontrol seen in childhood obesity is associated with leptin levels, insulin resistance,and increased oxidative stress and inflammation, and that these relationships areprimarily mediated by adipose tissue." (PMID 25119757, 2014). "Finally, we tested whether leptin and insulin resistance (HOMA-IR) mediated the association between activity in the left and right VS during the FID task and BMI." (PMID 25368558, 2014). "Increasing leptin might be regarded as a marker of risk as it has been associated with insulin resistance, increased secretion of proinflammatory cytokines, increased onset of depressive symptoms, T2DM, and estimated age-related cognitive change in elderly men." (PMID 25105135, 2014). "Moreover, AFs exposure may lead to significant reduction of leptin accompanied with high levels of cortisol, IL-6, and insulin resistance which together act to influence the feeding response, causing weight loss in patients with pancreatic cancer." (PMID 24959547, 2013). "Also leptin may be involved in cardiovascular risk, due to the association of serum levels with insulin resistance and the effect on atherosclerosis." (PMID 24376307, 2013). "However, the L:A ratio was reported to be correlated with insulin resistance and to possibly predict the risk of metabolic syndrome in the nondiabetic population, which might be due to a reciprocal response of leptin and adiponectin to increasing adiposity." (PMID 24245495, 2013). "Interestingly, leptin levels were suppressed at early time points in our model but secondarily increased to suprabasal levels at later time points and overall positively associated with insulin resistance." (PMID 19087258, 2008).
Insulin resistance (continued). "Dyslipidemia in PsA arises from multiple mechanisms, including systemic inflammation, insulin resistance, and imbalances in adipokines such as leptin, adiponectin, and resistin." (PMID 42187996, 2026). "In this sense, the leptin/adiponectin ratio (LAR) has been proposed as a surrogate marker of insulin resistance and adipose tissue dysfunction." (PMID 41528263, 2026). "Elevated leptin and reduced adiponectin levels contribute significantly to metabolic deterioration and insulin resistance." (PMID 41913855, 2026). "Leptin inhibits the function of iNKT cells through the MAPK pathway, and the disruption of leptin signalling exacerbates metabolic disorders such as insulin resistance." (PMID 41503874, 2026). "In terms of metabolic syndrome, activation of EPAC1 can improve insulin resistance and glucose homoeostasis in obese mice by promoting leptin secretion and enhancing leptin sensitivity." (PMID 41503874, 2026). "Excess visceral fat secretes proinflammatory cytokines (TNF-α, IL-6) and adipokines (leptin), which promote oxidative stress and insulin resistance." (PMID 40702394, 2025). "Research has also observed correlations between changes in ghrelin and changes in leptin, adiponectin, insulin, and insulin resistance, which are consistent with the expected direction of weight loss." (PMID 39917742, 2025). "The increase in body fat was accompanied by insulin resistance, adipocyte hypertrophy, and increased circulating levels of leptin and glucose." (PMID 39997751, 2025). "Insulin resistance, leptin expression, and pro-inflammatory genes directly correlated with VAT neutrophil abundance." (PMID 39861371, 2025). "Improvements were also seen in aggression, anxiety, and compulsivity, and there were reductions in leptin, insulin, and insulin resistance, as well as a significant increase in adiponectin." (PMID 40136445, 2025). "These beneficial effects were accompanied by improvements in insulin resistance and a reduction in plasma leptin and TNF-α concentrations, suggesting that these biomarkers play a relevant role in hepatic fat accumulation." (PMID 40862455, 2025). "Recent mechanistic insights include adipocytokine dysregulation, particularlyaltered leptin levels that can promote hepatic collagen production and exacerbate insulin resistance." (PMID 41393433, 2025). "Consistently elevated leptin levels were reported across studies, alongside evidence of cortisol dysregulation, altered androgen profiles, and insulin resistance." (PMID 40781762, 2025). "Leptin, through the induction of systemic inflammation, plays an important role in energy regulation, endocrine function (lipid metabolism and insulin resistance), immune response, and reproduction." (PMID 40725173, 2025). "Supplementation with MTE and MLE inhibited the elevation of LEP and INS caused by a high-fat diet and reduced insulin resistance, leptin resistance, and blood glucose levels." (PMID 40564320, 2025). "Leptin has been extensively studied in recent years as a potential marker of insulin resistance, a key component of diabetes and other metabolic disorders, including metabolic syndrome and polycystic ovary syndrome (PCOS)." (PMID 40630340, 2025). "Excess adipose tissue can elevate the expression of inflammatory cytokines (such as TNF-α) and adipokines (like leptin and resistin), both of which contribute to the pathogenesis of insulin resistance by disrupting insulin signaling and action." (PMID 40724174, 2025). "Taken altogether, thyroid dysfunction can worsen insulin resistance by altering adipokine levels, with hypothyroid patients often having high leptin and low adiponectin, impairing liver insulin signaling and fat buildup." (PMID 41411310, 2025). "Insulin resistance diminishes the liver’s response to insulin, disrupting glucose and lipid metabolism, while leptin resistance leads to energy imbalance, further exacerbating hepatic lipid accumulation." (PMID 40538532, 2025).
Insulin resistance (continued). "Other pathways include the insulin signaling pathway, genes regulating insulin resistance, and beta-cell proliferation, and hormonal regulation (leptin) interaction between the HPT axis and glucose metabolism." (PMID 40600010, 2025). "In the early stage of T2DM, a certain level of leptin resistance and insulin resistance can be observed, while the skeletal muscle Leptin-AMPK-ACC signaling pathway remains unaffected." (PMID 39877628, 2025). "Mechanisms involve serotonergic and dopaminergic signaling, receptor desensitization, insulin resistance, and altered leptin and ghrelin levels." (PMID 40444017, 2025). "Adipose tissue dysfunction, which is characterized by adipocyte hypertrophy, chronic inflammation, and altered secretion of leptin, plays a critical role in the development of insulin resistance and metabolic complications in individuals with T2D." (PMID 41329353, 2025). "Cord plasma leptin levels were also associated with cord CPR levels, a marker of fetal insulin resistance, consistent with previous reports." (PMID 40725173, 2025). "In adipose tissue, they promote adipogenesis, macrophage infiltration, and dysregulated adipokine secretion characterized by reduced adiponectin and increased leptin resistance, therefore amplifying systemic insulin resistance." (PMID 41487746, 2025). "Specifically, leptin levels are negatively correlated with insulin sensitivity, with elevated leptin contributing to insulin resistance." (PMID 39942768, 2025). "A recent study showed that leptin mediates insulin resistance, a fundamental factor in the development of T2DM and MetS." (PMID 39815341, 2025). "Diabetic control mice exhibited markedly elevated glucose levels, characteristic of db/db mice with severe insulin resistance and hyperphagia due to leptin dysfunction." (PMID 40895680, 2025). "Among the blood laboratory results, glucose, insulin, homeostatic model assessment of insulin resistance (HOMA-IR), high-density lipoprotein, total bilirubin, and leptin levels were significantly associated with the total PANSS score." (PMID 40048458, 2025). "The expression of leptin and ghrelin receptor genes in the hypothalamus was measured using real-time PCR, and insulin resistance was calculated using the HOMA/IR formula." (PMID 40087612, 2025). "Though slight increases in leptin are beneficial for fat metabolism, chronic hyperleptinemia triggers insulin resistance in uremic patients." (PMID 40725208, 2025). "This study aimed to investigate the effects of an 8-week regimen of garlic and stevia extract along with aerobic exercise on the expression of hypothalamic leptin and ghrelin receptor genes as well as insulin resistance and weight gain in obese rats." (PMID 40087612, 2025). "Leptin is also essential for central insulin signaling, meaning that individuals with excess adipose tissue commonly exhibit acquired insulin resistance." (PMID 40724604, 2025). "Excess adiposity is thought to impact on the cancer microenvironment and increase production of leptin, plasminogen activator inhibitor and endothelial growth factor, reduced adiponectin, insulin resistance and inflammation." (PMID 40745221, 2025). "These include the PPARγ, LEP, and fat mass and obesity-associated (FTO) genes, whose epigenetic modifications correlate with increased adipocyte differentiation, insulin resistance and altered energy balance." (PMID 41226484, 2025). "Transgenic mice with overexpression of IGFBP3 exhibited mild insulin resistance, accompanied by elevated levels of plasma leptin, glucose, and insulin." (PMID 40271123, 2025). "In human visWAT, we observed a positive correlation of MTCH2 expression (visMTCH2) with BMI, body fat, fasting plasma insulin (FPI), leptin, homeostatic model assessment for insulin resistance (HOMA-IR), and HDL-cholesterol." (PMID 41044057, 2025).
Insulin resistance (continued). "Regarding behavioral mechanisms, sleep deprivation resulting from long working hours induces insulin resistance and increases appetite by reducing leptin and elevating ghrelin levels, subsequently promoting weight gain." (PMID 41196923, 2025). "Metreleptin, a recombinant human leptin analog, has demonstrated efficacy in reducing hyperphagia and improving insulin resistance and its complications in patients with lipodystrophy." (PMID 40452043, 2025). "Peripheral insulin resistance drives hyperinsulinemia, which can exacerbate central insulin resistance by disrupting hypothalamic leptin signaling and glucose sensing." (PMID 41282294, 2025). "Placental growth hormone (GH-V) also induces maternal insulin resistance, whereas adipokines, such as leptin and adiponectin, also mediate insulin resistance." (PMID 41295371, 2025). "A study in obese children found that, at baseline, they had higher insulin resistance, elevated leptin, and lower PP levels compared to normal-weight children." (PMID 40214973, 2025). "Chronic inflammation in adipose tissue releases pro-inflammatory adipokines, such as resistin and leptin, which exacerbate insulin resistance." (PMID 41007787, 2025). "Hyperglycemia, insulin resistance, and hypoalbuminemia are common, while leptin and ghrelin levels are typically low." (PMID 40428308, 2025). "While IL-6 and TNF-α contribute directly to insulin resistance and inflammation, leptin plays an additional role in reproductive dysfunction by influencing ovarian steroidogenesis and follicular maturation." (PMID 40385768, 2025). "When compared to adiponectin, leptin acts in the opposite direction, with higher levels promoting insulin resistance and metabolic dysfunction." (PMID 40385768, 2025). "Excess visceral fat can secrete higher levels of hormones such as leptin and resistin, disrupting insulin signaling, aggravating insulin resistance, and impairing cholesterol metabolism and gallbladder function." (PMID 41287115, 2025). "Experimental studies have shown that circadian misalignment decreases leptin, increases glucose despite higher insulin levels, and inverts the cortisol rhythm, promoting insulin resistance and metabolic dysfunction." (PMID 39856244, 2025). "A previous study found a positive correlation of leptin with insulin resistance in participants with abnormal glucose tolerance (AGT)." (PMID 40630340, 2025). "Further investigations are warranted to explore the interactions between METS-IR and other metabolic biomarkers (e.g., fasting insulin, FFAs, leptin, adiponectin) to clarify the mechanistic pathways of insulin resistance in NAFLD pathogenesis." (PMID 40640543, 2025). "Adipose tissue is known to play a unique role in insulin resistance due to the production of adipokines, such as leptin and adiponectin, and the rise in circulating free-fatty acids." (PMID 40283443, 2025). "Our results indicated that leptin decreased with the morning HC dose, and we suspect that the development of steroid-induced insulin resistance also involves an impaired signalling dialogue between leptin and insulin." (PMID 40795401, 2025). "It has been demonstrated that leptin supplementation can improve insulin resistance and thus play a therapeutic role in T2DM." (PMID 39812542, 2025). "Importantly, the study was adequately controlled for major known metabolic confounders—age, gender, and insulin resistance—which improves the internal validity of the findings and supports the hypothesis of an independent association between leptin and hepatic fibrosis." (PMID 40507178, 2025). "Leptin levels rise under insulin resistance and hyperinsulinaemia, amplifying proliferative signalling and further decoupling tumour growth from endocrine restraint." (PMID 41586225, 2025).
Insulin resistance (continued). "Limited and dysfunctional peripheral fat depots along with relatively low levels of adipokines (such as leptin and adiponectin) in PL result in ectopic accumulation of fat and trigger the development of severe insulin resistance." (PMID 40520449, 2025). "This narrative review focuses on mechanisms linking ATD with T2DM through adipokine actions (specifically, leptin and adiponectin) on insulin resistance and glucose metabolism." (PMID 40722840, 2025). "In our longitudinal study, we identified a sharp increase in FGF21 early after surgery concomitant with a decrease in insulin resistance and serum leptin levels." (PMID 39885510, 2025). "improves levels of apolipoproteins A1 and B, oxidized low-density lipoproteins, leptin, malondialdehyde and C-reactive protein, while decreasing markers of insulin resistance." (PMID 40375997, 2025). "Similar to MAFLD, CKD patients exhibit excess FFAs and abnormal levels of adipokines (e.g., adiponectin, leptin, resistin, and omentin) in their circulation, leading to systemic insulin resistance in peripheral tissue." (PMID 40725208, 2025). "Leptin and resistin are involved in insulin resistance; however, reduced levels of adiponectin are unable to counter these effects." (PMID 41220583, 2025). "Insulin resistance, characterized by reduced responsiveness to insulin, can interfere with the normal signaling pathways of various hormones, including leptin." (PMID 40087612, 2025). "The results regarding changes in serum leptin concentrations revealed a statistically significant increase in maternal blood (MB) in the insulin resistance group compared to the healthy group (p < 0.0001)." (PMID 41007299, 2025). "TNF-α is a key cytokine released from adipocytes and is known to dysregulate leptin and inhibit glucose-stimulated insulin secretion leading to insulin resistance." (PMID 41463113, 2025). "Subsequent studies have revealed that HFDs promote hyperglycemia, hyperleptinemia, whole-body insulin resistance, and hypothalamic leptin resistance." (PMID 40690443, 2025). "Adipose tissue secretes various cytokines and hormones, such as leptin and adiponectin, which affect the insulin signaling pathway, leading to insulin resistance." (PMID 40574814, 2025). "Studies on animals with type 2 diabetes indicated that leptin replacement therapy improved insulin resistance and suppressed hepatic gluconeogenesis and fasting hyperglycemia." (PMID 40283443, 2025). "provides berberine, which lowers leptin levels, improves insulin resistance, reduces oxidative stress, and supports lipid metabolism." (PMID 41268159, 2025). "Increases in insulin resistance, leptin levels, and soluble leptin receptor levels, alongside declines in fasting glucose and adiponectin levels during pregnancy, were consistent with findings in both normal weight and obese cohorts in these studies." (PMID 41202005, 2025). "Future studies should collect data on insulin resistance, lipid profiles, and circulating adipokines (leptin, adiponectin, inflammatory cytokines) in endometriosis patients." (PMID 40565786, 2025). "Meanwhile, abdominal fat accumulation can activate the sympathetic nervous system, leading to abnormal secretion of adipokines like leptin, which contributes to insulin resistance and promotes chronic inflammation." (PMID 39815248, 2025). "Excess body weight and insulin resistance can impair leptin signaling, contributing to leptin resistance." (PMID 41334336, 2025). "In postmenopausal women, physical activity reduces adipose tissue, leptin levels, insulin resistance, and inflammatory markers such as TNF-α and IL-6, which are produced in adipose tissue." (PMID 40243654, 2025). "After 4 weeks of OLA treatment, SCZ patients experienced significant weight gain, deteriorating insulin resistance, and increased LEP levels." (PMID 39313903, 2025).